EGFR (epidermal growth factor receptor)
Diseases named in the same sentence as EGFR in open-access papers (continued):
Sharing a sentence is not in itself a finding about the gene and the disease.
cutaneous vasculitis (2 papers, 2022 to 2025). Inflammation of the blood vessel wall characterized by palpable purpura. "Over the past two decades, besides osimertinib, the primary EGFR-TKI drugs causing cutaneous vasculitis have been the first generation EGFR-TKIs, gefitinib and erlotinib, with a total of 14 cases reported." (PMID 39917172, 2025). "Based on these observations, we lean towards considering cutaneous vasculitis caused by EGFR-TKIs is a drug-induced hypersensitivity reaction." (PMID 39917172, 2025). "We also conducted a literature review cutaneous vasculitis induced by osimertinib and other EGFR-TKIs." (PMID 39917172, 2025). "Cutaneous vasculitis is a rare skin adverse reaction to EGFR-TKIs, and it is crucial to remain vigilant, identify it early, educate the patient, and manage it effectively." (PMID 39917172, 2025). "We searched the PubMed, MEDLINE, Elsevier ScienceDirect, and Web of Science databases to investigate and review existing literature reports and review articles on cutaneous vasculitis induced by EGFR-TKIs." (PMID 39917172, 2025). "Among the 18 cases of EGFR-TKI-induced cutaneous vasculitis listed in the previous tables, 16 cases (88.9%) discontinued the EGFR-TKI." (PMID 39917172, 2025). "Here, we report a case of osimertinib-induced cutaneous vasculitis and review the literature on cutaneous vasculitis induced by osimertinib and other EGFR-TKI drugs, aiming to provide a reference for the safe use of osimertinib." (PMID 39917172, 2025). "Reported cases of other EGFR-TKIs-induced cutaneous vasculitis." (PMID 39917172, 2025). "The average time from the start of EGFR-TKI treatment to the onset of cutaneous vasculitis is 8.7 ± 7.8 weeks, with a range of 1 week to 8 months, indicating that clinical manifestations and signs may have a delayed onset." (PMID 39917172, 2025). "Currently, there are 18 reported cases of EGFR-TKI (Osimertinib, Gefitinib, Erlotinib) induced cutaneous vasculitis." (PMID 39917172, 2025). "The mechanism by which EGFR-TKIs induced cutaneous vasculitis is not yet clear but is believed to be similar to other forms of cutaneous small vessel vasculitis, potentially mediated by immune complexes." (PMID 39917172, 2025). "After switching to the same class of EGFR-TKI, namely almonertinib, the patient experienced a mild, self-limiting rash and did not exhibit any further clinical signs of cutaneous vasculitis." (PMID 39917172, 2025).
cystic teratoma (2 papers, 2024 to 2025). "A mutation in the EGFR-V323I was identified in the original mature cystic teratoma of the ovary." (PMID 41322900, 2025).
Down syndrome (2 papers, 2017 to 2018). "EGFR gene has been reported to be dysregulated in the mouse model of Down syndrome (DS), with regulatory impacts on calcium signaling pathway, neuroactive ligand-receptor interaction, and the MAPK signaling pathway." (PMID 29351810, 2018).
ectodermal dysplasia (2 papers, 2018 to 2019). "To date, three cases of severe ectodermal dysplasia were reported to be caused by an inherited germline homozygous loss-of-function missense mutation of EGFR." (PMID 29899996, 2018). "Interestingly, the hypohidrotic ectodermal dysplasia phenotype is partially mediated by decreased EGFR signaling, which can possibly cause hypohidrosis." (PMID 31162134, 2019).
embryonal carcinoma (2 papers, 2022). A non-seminomatous malignant germ cell tumor characterized by the presence of large germ cells with abundant cytoplasm resembling epithelial cells, geographic necrosis, high mitotic activity, and pseudoglandular and pseudopapillary structures formation. "The activation status of the EGFR determines the timing by which neural progenitor cells derived from P19 embryonal carcinoma terminally differentiate into neurons." (PMID 36206843, 2022). "A previous study reported that 43% of chemorefractory embryonal carcinomas expressed EGFR." (PMID 35740662, 2022). "Thus, EGFR may be a good target for NIR-PIT in chemorefractory embryonal carcinoma." (PMID 35740662, 2022).
embryonal rhabdomyosarcoma (2 papers, 2011 to 2019). A poorly circumscribed morphologic variant of rhabdomyosarcoma. "Epidermal growth factor receptor (EGFR) is a receptor tyrosine kinase that has been shown to be expressed or activated in 32–50% of alveolar and 31–55% of embryonal rhabdomyosarcoma." (PMID 21559212, 2011).
enteritis (2 papers, 2021 to 2025). Inflammation of the small intestine. "The inhibition of EGFR phosphorylation by EGFR‐TKI is thought to exacerbate enteritis." (PMID 40641492, 2025).
erythema multiform (2 papers, 2023). "Other selected cutaneous AEs, such as erythema multiform, maculopapular rash, and skin exfoliation, were more frequent among anti-PD-1/L1 plus VEGFR/EGFR inhibitor combination therapy than other ICI combination regimens and required more attention from oncologists and dermatologists." (PMID 37332342, 2023).
Erythroblastic Leukemia (2 papers, 2023 to 2025). "HB-EGF exerts its effects by binding to the EGF receptor (EGFR), which is also called ERBB1 (Erythroblastic Leukemia Viral Oncogene Homolog 1)." (PMID 40149770, 2025).
familial breast cancer (2 papers, 2016 to 2023). "Nevertheless, we were unable to identify, at the time of writing, studies that have evaluated EGFR as a prognostic marker in familial breast tumours, or the benefits of EGFR-targeted tyrosine kinase inhibitors, specifically in clinical familial breast cancer studies." (PMID 36831687, 2023).
fibromatosis (2 papers, 2017 to 2025). A poorly circumscribed neoplasm arising from the soft tissues. "EGFR signaling has been implicated in the pathogenesis of fibromatosis in previous studies of diseased tissues from patients with DD." (PMID 29104234, 2017). "Co-expression of EGFR protein and TGF-alpha has been found in proliferating myofibroblasts in palmar fibromatosis nodules of DD patients." (PMID 29104234, 2017).
gallbladder tumor (2 papers, 2019 to 2022). "In conclusion, our study showed that a fluorescent EGFR-targeted antibody can be used successfully for the diagnosis of gallbladder tumors, which in turn can help detect malignant disease." (PMID 35701793, 2022). "In vivo imaging of subcutaneous and orthotopic gallbladder tumors was performed after the injection of DyLight 650- or 800-conjugated EGFR antibody." (PMID 35701793, 2022). "Our study showed that fluorescent EGFR antibodies and the Firefly camera in the da Vinci system can detect fluorescing gallbladder tumors, which demonstrates their potential use for molecular imaging-based prevision surgery in the near future." (PMID 35701793, 2022). "Our results showed that anti-EGFR specifically bound to gallbladder tumors and produced fluorescence, which could be detected by imaging during surgery in real time." (PMID 35701793, 2022). "In addition, using 800-nm fluorescent EGFR antibody FireflyTM camera in da Vinci® robotic surgery system could detect fluorescent signal from gallbladder tumor, suggesting that its use is not limited to robotic surgery, but can also be expanded to laparoscopic and endoscopic system." (PMID 35701793, 2022). "In vitro and in vivo fluorescent EGFR antibody could make EGFR-positive gallbladder tumor fluorescent; however, when no tumor was made or EGFR was not expressed, no fluorescence was emitted." (PMID 35701793, 2022).
gallstones (2 papers, 2019 to 2025). Solid crystalline precipitates in the biliary tract, usually formed in the gallbladder, resulting in the condition of cholelithiasis. "Estrogen can also activate G protein-coupled receptor 30 through the signaling cascade of epidermal growth factor receptor, which inhibits cholesterol 7α-hydroxylase activity and bile acid synthesis, leading to an increase in cholesterol secretion and promoting gallstone formation." (PMID 39897593, 2025).
ganglioglioma (2 papers, 2023 to 2025). A well differentiated, slow growing neuroepithelial neoplasm composed of neoplastic, mature ganglion cells and neoplastic glial cells. "Here, we present a case of a VOPP1::EGFR fusion associated with downstream NFκB pathway activation as a novel molecular alteration in ganglioglioma." (PMID 40234994, 2025). "Here, we report for the first time a gene fusion between epidermal growth factor receptor (EGFR) and vesicular, overexpressed in cancer, prosurvival protein 1 (VOPP1) as a potential oncogenic driver in a glioneuronal tumor morphologically resembling ganglioglioma." (PMID 40234994, 2025). "Since there is no histological or molecular evidence supporting the diagnosis of other glioneural tumors (e.g., PLNTY, DNT, gangliocytoma), the tumor should be regarded as a glioneural tumor with histological features of ganglioglioma and VOPP1::EGFR fusion, not elsewhere classified (NEC)." (PMID 40234994, 2025).
gastric cardia adenocarcinoma (2 papers, 2021 to 2023). A carcinoma that arises from glandular epithelial cells of the cardia of stomach. "As focal amplification was mainly driven by ecDNA, the detection of ERBB2 and EGFR ecDNAs should be considered as potential prognostic biomarkers in gastric cardia adenocarcinoma." (PMID 37448518, 2023). "In gastric cardia adenocarcinoma, focal amplification of ERBB2 is correlated with a better prognosis, whereas focal amplification of EGFR is associated with a worse prognosis." (PMID 37448518, 2023).
gastrinoma (2 papers, 2011 to 2024). "EGFR overexpression is associated with aggressive types of gastrinoma-functional PNET, similar to PDAC." (PMID 38793045, 2024).
gastroesophageal reflux disease (2 papers, 2022 to 2025). A chronic disorder characterized by reflux of the gastric and/or duodenal contents into the distal esophagus. "It is worth noting that some studies have not demonstrated a clear correlation between EGFR expression and the progression of reflux esophagitis, BE, or EAC, suggesting that this relationship is complex and likely influenced by multiple factors." (PMID 40149421, 2025).
gastrointestinal carcinoma (2 papers, 2010 to 2012). "EGFR amplification has been suggested to be associated with prognosis in gastrointestinal carcinoma." (PMID 22139134, 2012).
Hearing impairment (2 papers, 2024 to 2025). A decreased magnitude of the sensory perception of sound. "Additional newer EGFR inhibitors with better specificity and PK/PD characters than afatinib and zorifertinib may therefore have potential as otoprotectants against NIHL and other forms of hearing loss." (PMID 38896614, 2024).
hidradenocarcinoma (2 papers, 2012 to 2015). A carcinoma with apocrine and less often eccrine differentiation, arising from the sweat glands. "On immunohistochemistry, hidradenocarcinomas are variably positive for androgen receptor (AR), estrogen receptor (ER), progesterone receptor (PR), EGFR (epidermal growth factor receptor), and HER-2 (human epidermal growth factor receptor 2)." (PMID 25815059, 2015). "The current focus for treatment of hidradenocarcinoma is on targeted therapies like trastuzumab, EGFR (epidermal growth factor receptor) inhibitors, PI3K/Akt/mTOR pathway inhibitors, hormonal agents like antiandrogens and electrochemotherapy but more future trials are required." (PMID 25815059, 2015). "Although the majority (85%, 44/52) of apocrine-eccrine carcinomas in our series demonstrated EGFR protein overexpression, only EGFR trisomy or polysomy (13/47, 28%) and no gene amplification were documented by FISH, most frequently noted in eccrine carcinoma, hidradenocarcinoma and porocarcinoma." (PMID 23056620, 2012).
hydatidiform mole (2 papers, 2017 to 2020). A gestational trophoblastic disorder characterized by marked enlargement of the chorionic villi, hyperplasia of the villous trophoblastic cells and hydropic changes. "Previous studies have reported that EGFR is correlated with the development of hydatidiform moles and is also highly expressed in hydatidiform moles." (PMID 32575164, 2020). "As EGFR promotes the proliferative and invasive properties of trophoblasts, its overexpression associated with the proper organization of the trophoectodermal layer can suggest a higher invasive potential of AND placentae, resembling what is generally observed in hydatidiform moles." (PMID 29190766, 2017).
hyperthyroidism (2 papers, 2023 to 2024). Overactivity of the thyroid gland resulting in overproduction of thyroid hormone and increased metabolic rate. "Pro-Epidermal Growth Factor (EGF) is an essential growth factor in thyroid tissue, and nuclear EGFR expression is elevated in GD tissue samples, implying that the EGFR-dependent modulation of thyroid cell proliferation under physiological conditions may be associated with hyperthyroidism." (PMID 37859983, 2023).
hypertriglyceridemia (2 papers, 2022 to 2025). A laboratory test result indicating elevated triglyceride concentration in the blood. "Rs4845625 was found to be significantly associated with hypertriglyceridemia in the Japanese population, and the T allele was associated with a lower serum concentration of creatinine and increased EGFR." (PMID 35330392, 2022).
hypopharyngeal squamous cell carcinoma (2 papers, 2020 to 2023). "The cytotoxic function of CAR-T cells targeted to EGFR against hypopharyngeal squamous cell carcinoma was verified as well in a preclinical study conducted by a team which had already successfully built and verified EGFR-CAR-T-cells." (PMID 37457699, 2023). "The EGFR-target CAR-T cells targeted to hypopharyngeal squamous cell carcinoma have been reported to acquire an encouraging effect." (PMID 32775421, 2020).
hypospadias (2 papers, 2023 to 2025). Hypospadias is the displacement of the urethral meatus on the ventrum of the penis. "A correlation between the low expression level of EGF, EGFR, and HOXA13 in the foreskin tissue and hypospadias cases indicates a possible cause of hypospadias." (PMID 37238140, 2023). "In the study by Elbakry et al16, expression of EGFR was decreased in both layers, suggesting that either layer can be utilized for hypospadias repair without a significant preference." (PMID 40434280, 2025).
hypothyroidism (2 papers, 2025). Abnormally low levels of thyroid hormone. "EGFR-dependent autophagy mechanism and the heparin-binding EGF-like growth factor (HB-EGF) are crucial for the loss of neurons and functional impairment in the cerebellum during developing hypothyroidism." (PMID 40237055, 2025).
inflammatory skin disease (2 papers, 2019 to 2024). Inflammatory skin disorders covers a broad category that includes many conditions ranging in severity, from mild itching to grave medical health complications These disorders are common in people of all ages and races. "The GRB2 gene is critical in the downstream transduction of EGFR, and the aberrant expression of the latter has been implicated in several inflammatory skin diseases." (PMID 31569353, 2019). "The role of EGFR tyrosine Kinases signaling pathway in inflammatory skin diseases including AA is poorly understood and has not been yet investigated in clinical trials before." (PMID 38454571, 2024).
intestinal gastric adenocarcinomas (2 papers, 2016). "In intestinal-type adenocarcinoma, we found that high HER3 expression was a favourable prognostic factor and that high EGFR expression was an adverse prognostic factor, although none of these associations were independent of other prognostic factors." (PMID 27070783, 2016).
intestinal type adenocarcinoma (2 papers, 2014 to 2016). An adenocarcinoma arising from epithelium which has undergone intestinal metaplasia. "Additionally, there was a significantly higher percentage of EGFR-positive cases among intestinal-type carcinomas." (PMID 24454858, 2014).
intimal sarcoma (2 papers, 2019). A malignant neoplasm arising from the large blood vessels. "Another study of IS, which was the first to propose PDGFRA as a molecular hallmark for intimal sarcomas, found copy number gains of PDGFRA, EGFR, and MDM2 in 8 patients using FISH and aCGH with consistent activation of PDGFR and EGFR confirmed by western blotting." (PMID 31480474, 2019).
Jaundice (2 papers, 2018 to 2024). Yellow pigmentation of the skin due to bilirubin, which in turn is the result of increased bilirubin concentration in the bloodstream. "It is speculated that the YCSND can treat jaundice by inhibiting the expression of c-jun, RELA, EGF, and EGFR." (PMID 30671125, 2018).
joint disease (2 papers, 2013 to 2014). "The influence of endogenous EGFR regulation on joint disease progression after trauma to ligaments and menisci has been unexplored." (PMID 24670222, 2014). "We examined the effect of EGFR modulation by MIG-6 on joint disease development after ligament and meniscus injury." (PMID 24670222, 2014). "The role of endogenous EGFR regulation during joint disease due to ligament and meniscal trauma is unknown." (PMID 24670222, 2014).
keratinization disease (2 papers, 2023 to 2024). "Overactive EGFR signaling plays a role in different keratinizing disorders with palmoplantar keratoderma (PPK), like pachyonychia congenita (most significant in the category ‘Disease’ in our functional enrichment results)." (PMID 38675137, 2024). "In contrast to keratinizing disorders, lesional AD skin exhibited decreased expressions levels of EGFR." (PMID 38675137, 2024). "Since then, endotypes underlying novel entities matching the concept of autoinflammatory keratinization diseases have been discovered (mutations of JAK1, POMP, and EGFR)." (PMID 38103162, 2023).
kidney injury (2 papers, 2022 to 2023). Trauma to the kidney. "Many experiments have found that EGFR and its different ligands are upregulated and that EGFR activation occurs in renal cells cultured in a high glucose environment and in experimental diabetic models (kidney injury)." (PMID 36483738, 2022). "EGFR activation is well known to induce cell dedifferentiation and proliferation, and our results indicate that these properties mediate its essential function in the development of interstitial fibrosis in response to kidney injury." (PMID 37963889, 2023).
left ventricular hypertrophy (2 papers, 2013 to 2025). Enlargement of the LEFT VENTRICLE of the heart. "A study found that EGFR activation is linked to cardiac remodeling, and antisense inhibition of EGFR can prevent the development of left ventricular hypertrophy." (PMID 40552149, 2025).
Leukocytoclastic vasculitis (2 papers, 2019 to 2025). "Some researchers suggested that dapsone is an effective targeted therapy for cutaneous leukocytoclastic vasculitis that does not compromise the immune system and allows the continuation of EGFR-TKI therapy." (PMID 39917172, 2025).
listeriosis (2 papers, 2022). A bacterial infection caused by Listeria monocytogenes. "In fact, the only case of listeriosis associated with inhibitors of the EGFR/HER2 pathway in the literature was a patient with metastatic breast cancer who received trastuzumab and lapatinib." (PMID 35572995, 2022). "These two patients represent the second and third reports of listeria infections associated with EGFR/HER2 pathway inhibitors in the literature." (PMID 35572995, 2022). "The two patients in the present cohort who received gefitinib/osimertinib/afatinib and trastuzumab/lapatinib, respectively represent the second and third cases of patients with listeria infections related to inhibitors of the EGFR/HER2 pathway." (PMID 35572995, 2022). "Therefore, these compounds could be considered for use as a potential treatment for listeriosis by inhibiting proteins such as, IL2, MAPK1, SRC, EGFR, PTPRC, TNF, IL1B, and ERBB2." (PMID 36671206, 2022).
lung carcinoids (2 papers, 2022 to 2024). "Elevated EGFR expression was more prominent in lung carcinoid tumors than in carcinomas, and upregulated EGFR expression was significantly associated with lower IASLC-Grade (p = 0.0005)." (PMID 38539512, 2024).